CDC27 (cell division cycle 27)
Diseases named in the same sentence as CDC27 in open-access papers (continued):
Sharing a sentence is not in itself a finding about the gene and the disease.
renal cell carcinoma (2 papers, 2019 to 2024). "Module 2 included NEDD4, CDC27, UBE2E2, and TCEB1 associated with ubiquitin-mediated proteolysis and renal cell carcinoma pathways." (PMID 31178673, 2019).
thymoma (2 papers, 2023). A neoplasm arising from the epithelial cells of the thymus. "Our findings revealed previously unreported CDC27 and FGFR1 mutations in thymoma." (PMID 37828033, 2023). "The mutation frequencies of CDC27 (67% vs. 29%), CTNND2 (33% vs. 4%), KRTAP6‐1 (33% vs. 4%), and RERE (33% vs. 4%) trended to be higher in type B3 thymoma than other subtypes of thymomas, while the mutation frequency of MUC5B (0% vs. 32%) trended to be lower in type B3 thymoma." (PMID 36916520, 2023).
acute lymphoblastic leukemia (1 paper, 2025). Leukemia with an acute onset, characterized by the presence of lymphoblasts in the bone marrow and the peripheral blood. "In addition, CDC27 has been reported to be upregulated in patients with acute myeloid leukemia (AML) or acute lymphoblastic leukemia (ALL)." (PMID 39984622, 2025).
ataxic disorders (1 paper, 2020). "Furthermore, a literature review did not reveal any evidence for a relationship between the CDC27 and our family's phenotypes including migraine, vertigo, vestibular or ataxic disorders." (PMID 33193064, 2020).
autoimmune disease (1 paper, 2022). A disorder resulting from loss of function or tissue destruction of an organ or multiple organs, arising from humoral or cellular immune responses of the individual to their own tissue constituents. "Abnormal CDC27 expression is associated with autoimmune diseases and cancer, and it can help significantly in predicting breast cancer recurrence." (PMID 35418986, 2022). "CDC27 expression is abnormal in several tumors and autoimmune diseases, and their pathogenesis may be related to APC/C activation." (PMID 35418986, 2022).
Autoimmunity (1 paper, 2024). The occurrence of an immune reaction against the organism's own cells or tissues. "Moreover, targets such as CD37, CD47, B7-H6, CDC27, TCRVβ, and CCR8, when employed in CAR-T cells, present minimal risks of fratricide and autoimmunity." (PMID 38915099, 2024).
bipolar disorder (1 paper, 2022). A disorder of the brain that causes unusual shifts in mood, energy, activity levels and the ability to carry out day-to-day tasks. "In-depth analysis of the top 15 high-impact SNPs also confirmed an overlap between genotypes, with only three genes with confirmed SNPs related to neurological diseases (FRG2C for bipolar disorder, and CDC27 and KIR2DL4 for white matter microstructure measurements)." (PMID 35792828, 2022).
breast tumor (1 paper, 2017). "Importantly, CDC27 has been associated with securin expression and serve as an inverse predictor for the presence of malignant cells and shortened survival in human breast tumor cases." (PMID 27974673, 2017).
bronchiectasis (1 paper, 2025). Segmental, irreversible dilation of the bronchial tree resulting in the accumulation of secretions which leads to obstruction. "Therefore, this study aimed to investigate the expression and underlying molecular mechanisms of TFDP1 and CDC27 in bronchiectasis." (PMID 41458288, 2025). "To further investigate the relationship between TFDP1 and CDC27, we divided 71 patients with bronchiectasis into two groups based on the median expression level of TFDP1 (36 patients with high TFDP1 expression and 35 patients with low TFDP1 expression)." (PMID 41458288, 2025). "We found that the expression of TFDP1 and CDC27 in the bronchiectasis group was higher than that in the control group (p < 0.01)." (PMID 41458288, 2025). "Concurrently, we analyzed the correlation between TFDP1 and CDC27 and other clinical indicators in bronchiectasis." (PMID 41458288, 2025). "The present study provides novel insights into the molecular mechanisms underlying bronchiectasis by identifying TFDP1 and CDC27 as key genes that are upregulated in this chronic respiratory disease." (PMID 41458288, 2025). "CDC27 expression level in bronchiectasis was negatively correlated with leukocyte (r = −0.3381, p < 0.05), neutrophil (r = −0.2768, p < 0.05), and absolute monocyte (r = −0.3259, p < 0.05) counts." (PMID 41458288, 2025). "TFDP1 and CDC27 were significantly upregulated in patients with bronchiectasis (p < 0.01) and exhibited a strong positive correlation (r = 0.6104, p < 0.0001)." (PMID 41458288, 2025). "Regulatory relationships were assessed using ChIP‐seq data (Cistrome DB), and pathway enrichment was performed using clusterProfiler to explore the potential molecular mechanisms of action of TFDP1 and CDC27 in non‐CF bronchiectasis." (PMID 41458288, 2025). "In the GSE97298 dataset, the expression levels of TFDP1 and CDC27 in the bronchiectasis group were significantly higher than those in the control group (p < 0.01)." (PMID 41458288, 2025). "High expression of TFDP1 was often accompanied by high expression of CDC27 in the bronchiectasis group." (PMID 41458288, 2025). "To verify the expression of TFDP1 and CDC27 in bronchiectasis, we measured their expression in the peripheral blood of patients with bronchiectasis at the mRNA level." (PMID 41458288, 2025). "Our findings demonstrated that both chip datasets and clinical samples showed that TFDP1 and CDC27 were significantly overexpressed in peripheral blood samples of patients with bronchiectasis compared with healthy controls, with a strong positive correlation between their expression levels." (PMID 41458288, 2025). "Our study also explored cell cycle regulation, which may be an important mechanism by which TFDP1 and CDC27 participate in bronchiectasis development." (PMID 41458288, 2025). "This study focuses on the changes in the expression levels of TFDP1 and CDC27 in bronchiectasis and their clinical significance and explores the molecular mechanisms of their mutual regulation in the occurrence and development of bronchiectasis." (PMID 41458288, 2025). "Transcription factor DP‐1 (TFDP1) and cell division cycle protein 27 (CDC27), which are implicated in tumorigenesis and cell cycle regulation, have not been explored in bronchiectasis." (PMID 41458288, 2025). "After the currently recognized treatment of bronchiectasis, such as antibiotics, airway clearance, immune regulation, and other treatments, how TFDP1 and CDC27 change and whether some drugs that affect the cell cycle can be used to treat bronchiectasis need further research." (PMID 41458288, 2025). "In summary, the current study revealed that TFDP1 and CDC27 were highly expressed in the bronchiectasis group and highlighted the potential regulatory effects of TFDP1 on CDC27." (PMID 41458288, 2025).
bronchiectasis (continued). "This study demonstrated the synergistic upregulation of TFDP1 and CDC27 in bronchiectasis and explored cell cycle regulation as an important potential mechanism by which TFDP1 and CDC27 contribute to the development of bronchiectasis." (PMID 41458288, 2025). "The roles of TFDP1 and CDC27 in diseases were mostly concentrated in tumor‐related diseases, but the roles in bronchiectasis have not been reported." (PMID 41458288, 2025). "However, the expression of TFDP1 and CDC27 in bronchiectasis and their relationship have not yet been reported." (PMID 41458288, 2025).
cervical cancer (1 paper, 2021). A primary or metastatic malignant neoplasm involving the cervix. "Conversely, higher expression of CDC27 in irradiated C33A (cervical cancer cell line) compared to SiHa cell line causes more cell death." (PMID 33750395, 2021). "It has been shown that reduced expression of CDC27 in irradiated SiHa cell line (cervical cancer cell line) promotes cell survival." (PMID 33750395, 2021).
esophageal squamous cell carcinoma (1 paper, 2021). Esophageal squamous cell carcinoma (ESCC) is a type of esophageal carcinoma (EC) that can affect any part of the esophagus, but is usually located in the upper or middle third. "The somatic and germline variations in CDC27 in esophageal squamous cell carcinomas (ESCC) were key regulators that have been suggested to affect mutational processes." (PMID 33750395, 2021).
hepatocellular carcinoma (1 paper, 2023). A malignant tumor that arises from hepatocytes. "For example, lncRNA RP11-286H15.1 binds to PABP cytoplasmic 4 (PABPC4) and promotes its ubiquitination, thus reducing the stability of tripartite motif-containing protein 37 (TRIM37) and cell division cycle protein 27 (CDC27) mRNAs in hepatocellular carcinoma (HCC) cells." (PMID 37225681, 2023).
lymphoma (1 paper, 2020). A malignant (clonal) proliferation of B- lymphocytes or T- lymphocytes which involves the lymph nodes, bone marrow and/or extranodal sites. "Although many studies have shown that CDC27 mutations are detected in various cancer specimens, the role of CDC27 in cancer is uncertain, especially in lymphoma." (PMID 32391258, 2020). "The expression and effect of CDC27 in lymphoma has not been reported or clarified." (PMID 32391258, 2020).
male infertility (1 paper, 2022). The inability of the male to effect fertilization of an ovum after a specified period of unprotected intercourse. "PSME3, PSMD3, and CDC27 were the top 3 hub genes identified within the male infertility network." (PMID 35918717, 2022).
malignant glioma (1 paper, 2022). A grade III or grade IV glioma arising from the central nervous system. "Recurrent malignant gliomas patients with CDC27 mutations were more sensitive to immunoadjuvants and reirradiation therapy." (PMID 35903675, 2022).
melanoma (1 paper, 2002). A malignant, usually aggressive tumor composed of atypical, neoplastic melanocytes. "For example, CDC27, which participates in mitosis, is an MHC class II-restricted tumour antigen in melanoma." (PMID 12177805, 2002).
meningioma (1 paper, 2017). A generally slow growing tumor attached to the dura mater. "Other than NF2, the most frequently mutated genes were CDC27 and LRP1B, mutated in 10 (9%) and 9 (8%) samples, respectively, of the total set of 115 meningiomas." (PMID 28713588, 2017).
mental retardation syndrome X-linked (1 paper, 2021). "Apart from that of the known molecular marker IDH1, we found that the status of cell division cycle 27 (CDC27), podocon (PODN), α-thalassemia/mental retardation syndrome X-linked (ATRX) and ryanodine receptor type 1 (RYR1) was significantly different between the two subgroups (P<0.05)." (PMID 34025640, 2021).
metastatic tumor (1 paper, 2022). "The results indicated that the mRNA expression of CDC27 was upregulated in the paired metastatic tumor tissues compared to the primary tumor tissues." (PMID 35242701, 2022).
multiple myeloma (1 paper, 2025). "In this study we performed machine learning in the RNA microarray data of purified myeloma plasma cell samples from five independent MM cohorts with 957 MM patients, and identified O-GlcNAcylation transferase (OGT) and cell division cycle 27 (CDC27) as the key prognostic genes for MM." (PMID 39984622, 2025).
NK/T-cell lymphoma (1 paper, 2021). "We identified four ENKTL markers (ZNF141, FCGR2C, NES and CDC27) in patients with extranodal NK/T-cell lymphoma." (PMID 34872521, 2021).
osteoporosis (1 paper, 2019). A condition of reduced bone mass, with decreased cortical thickness and a decrease in the number and size of the trabeculae of cancellous bone (but normal chemical composition), resulting in increased fracture incidence. "Excluding genes without known specific functions (CDC27 and TNRC18), ARID2, HEBP1, LTBP1, and PLVAP were the only significant differences in the cancer group revealed by the gene-score methodology, while DFFA, FAM193A, and VEGFA were the only significant differences in the osteoporosis group." (PMID 31747953, 2019).
prostate tumors (1 paper, 2021). "CDC27-OAT intrachromosomal fusion between CDC27 as a cell cycle regulator and OAT (ornithine aminotransferase, an enzyme which produces ornithine) in aggressive prostate tumors was identified in some patients." (PMID 33750395, 2021).
sarcoma (1 paper, 2018). A usually aggressive malignant neoplasm of the soft tissue or bone. "FRG1B and CDC27 were highly mutated in CKS samples, but in only 3 and 0.4%, respectively, of TCGA sarcoma samples." (PMID 30598078, 2018).
spinal chordoma (1 paper, 2021). A slow-growing malignant bone tumor arising from the remnants of the notochord and occurring in the spine. "Our analysis of 32 spinal chordomas identified alterations in LYST, PTEN, CDC27, and ARID1A at similar frequencies compared with their spinal chordoma cohort." (PMID 33543146, 2021).
squamous cell cervix carcinoma (1 paper, 2017). "In fact, lower expression CDC27 was found to be associated with poorer response to radiotherapy in squamous cell cervix carcinoma and Triple Negative Breast Cancer (TNBC) cells because of the important role of CDC27/APC in the mitotic regulatory pathway." (PMID 27974673, 2017).
T cell lymphoma (1 paper, 2020). "To test whether CDC27 alterations could affect the proliferation of T-LBL, we first examined the expression of CDC27 in five T cell lymphoma cell lines and primary normal T cells extracted from peripheral blood mononuclear cells using western blotting." (PMID 32391258, 2020).
T-lymphoblastic lymphoma (1 paper, 2021). The most frequent type of lymphoblastic lymphoma. "High levels of CDC27 were witnessed in T-lymphoblastic lymphoma (T-LBL)." (PMID 34872521, 2021).
thyroid cancer (1 paper, 2022). "CDC27 is involved in the regulation of cell mitosis, and is generally highly expressed in thyroid cancer." (PMID 35865459, 2022). "Using a computer algorithm to identify major driver mechanisms in our PTC cohort, the results showed that, in addition to BRAF mutations, NF1, PMS2, CDC27 and PPP4R2 gene mutations are also involved in the development of thyroid cancer, and joint mutations often occur." (PMID 35865459, 2022).
tongue cancer (1 paper, 2026). A malignant neoplasm affecting the tongue. "CDC27 together with BCLAF1 and AQP7 show substantial changes in HPV-related tongue cancers, especially CDC27 deletions that correlate with tumour recurrence." (PMID 41487403, 2026).
tumor (46 papers, 2012 to 2026). "Only three genes were mutated in more than two tumor samples-CDC27 (part of the anaphase-promoting complex, tumor suppressor), USP8 (deubiquitinase gene, cell cycle involvement), and NF2." (PMID 36672540, 2022). "In this tumor, CDC27 variants (including p.G265D/rs7350889) were suggested as possible drivers of tumorigenesis." (PMID 33750395, 2021). "The CDC27 tumor-specific and coding somatic variants in calcifying fibrous tumor of the pleura were suggested to have a role in the tumorigenesis and molecular pathogenesis of this cancer." (PMID 33750395, 2021). "In Osteosarcoma, (OS) pathogenic p.E6G CDC27 Tier 1 somatic mutation was suggested to have an important role in regulating OS tumor cell division and suggested as potential biomarker for OS." (PMID 33750395, 2021). "A study has identified mutated CDC27 as a tumor antigen which leaded to massive changes of chromosomal number." (PMID 32391258, 2020). "In conclusion, our study is the first to demonstrate that CDC27 is associated with tumor proliferation and progression in CRC." (PMID 26821069, 2016). "In conclusion, we found a specific CDC27 variant unique for tumours of HPV+ OPSCC patients with relapse, as well a common mutational signature for HPV+ OPSCC patients independent of the outcome, comprising keratin-associated proteins and mucins, but also specific variants, such as a BCLAF1 variant." (PMID 35008243, 2021). "Interestingly, CDC27, where a unique variant was found that was specific for tumours from patients with a recurrence, was also among the most commonly mutated genes." (PMID 35008243, 2021). "To further investigate and prove this connection, we also performed the western blotting, luciferase gene reporter assays and immunofluorescence staining, the results of which also proved our assumption that the expression of CDC27 is indirectly associated with PD-L1 in T-LBL tumor cells." (PMID 32391258, 2020). "OBSCN was associated with HCC tumor thrombectomy, while CDC27 was associated with recurrence." (PMID 32157118, 2020). "Moreover, the results revealed that CDC27 expression was significantly associated with tumor size (P=0.035), TNM stage (P=0.013), and distant metastasis (P=0.03)." (PMID 26821069, 2016). "All of the CDC27 mutations we identified were missense variants, characterized by a consistently low frequency of mutant allelic reads (8–14%), consistent with CDC27 mutation being present only in a subclone of each tumour sample." (PMID 25609015, 2015). "Therefore, additional studies may be necessary to determine which CDC27 isoform in which tumor subtype has the strongest association with prognosis." (PMID 33750395, 2021). "First, recent studies have demonstrated that CDC27 mutations are involved in various cancers; thus, we sought to investigate the presence of important disease-associated alleles, although we have not yet identified key mutations that can significantly affect tumor proliferation or progression." (PMID 26821069, 2016). "In our previous studies, we have reported that CDC27 promoted tumor progression and served as an independent prognostic factor in colorectal cancer." (PMID 35242701, 2022). "The analysis indicated that six genes (PIK3CA, CDC27, B2M, PTEN, SMAD4, and IL32) were strongly associated with tumor-infiltrating lymphocytes." (PMID 35903675, 2022). "To demonstrate the role of CDC27 in NB metastasis, we first detected CDC27 expression in primary NB and paired metastatic tumor tissues." (PMID 35242701, 2022). "The fact that a deletion in CDC27 was common (5/17, 29%) in and specific to the primary tumours of patients that relapsed is a novel finding of great interest." (PMID 35008243, 2021). "The only variant enriched (p < 0.05) in recurrent samples was a high-impact deletion in the CDC27 gene, being found in 5/17 primary tumours of patients with recurrence, as well as in one local relapse while being absent from all nonrecurrent patient samples." (PMID 35008243, 2021).